ROCK2 (Rho associated coiled-coil containing protein kinase 2)
Diseases named in the same sentence as ROCK2 in open-access papers (continued):
Sharing a sentence is not in itself a finding about the gene and the disease.
medulloblastoma (1 paper, 2019). A malignant, invasive embryonal neoplasm arising from the cerebellum. "The highest expression of ROCK1 was found in the Shh group while mRNA levels of ROCK2 were highest in Group 4 medulloblastomas." (PMID 31888022, 2019). "To confirm ROCK2-specific effects on medulloblastoma growth we performed siRNA experiments, and indeed observed a significant decrease in cell viability after ROCK2 downregulation." (PMID 31888022, 2019). "Publicly available expression cohorts on cell lines showed mRNA expression of both ROCK1 and ROCK2 in all accessible medulloblastoma cell lines: UW228, D283, D458, D425, and DAOY." (PMID 31888022, 2019). "The expression of ROCK1 and ROCK2 showed significant differences between different molecular subgroups of medulloblastoma." (PMID 31888022, 2019). "siRNA-mediated down-regulation of ROCK2 expression significantly suppressed the cell viability of medulloblastoma cells." (PMID 31888022, 2019). "Our analysis of expression arrays showed that Group 4 medulloblastomas have the highest mRNA expression of ROCK2 among the subgroups." (PMID 31888022, 2019). "Western blot analysis for ROCK1 and ROCK2 in a panel of medulloblastoma cell lines showed evident levels of protein expression from at least one of the two ROCKs in all cell lines analyzed, as well as activation of the downstream target MLC, however very low in the D458 cell line." (PMID 31888022, 2019). "This suggests a possible role for ROCK2 in medulloblastoma metastasis." (PMID 31888022, 2019). "In a study comparing the proteome and phosphoproteome landscape in medulloblastoma, Group 4 medulloblastomas were shown to express high levels of protein and phosphorylation of the guanine-nucleotide exchange factors (GEFs), as well as proteins signaling downstream of GEFs including ROCK2." (PMID 31888022, 2019). "To further investigate the involvement of the ROCK2 in the decreased medulloblastoma cell growth upon treatment with RKI-1447, we inhibited ROCK2 using small interfering RNA (siRNA) targeting ROCK2." (PMID 31888022, 2019). "In order to explore the importance of Rho/ROCK signaling in medulloblastoma, we analyzed mRNA expression levels of the downstream Rho activating kinases ROCK1 and ROCK2 in two different cohorts of medulloblastoma tissue samples, and in fetal and adult cerebellum." (PMID 31888022, 2019). "Here, we show that ROCKs are expressed in medulloblastoma, with higher ROCK2 mRNA expression in metastatic compared to non-metastatic tumors." (PMID 31888022, 2019).
mesangial sclerosis (1 paper, 2024). "Experiments using selective ROCK2 inhibitors in rodent models of kidney disease generally have preventive actions on the disease process, including reducing albuminuria and mesangial sclerosis, as well as decreasing GBM thickness." (PMID 38565675, 2024).
mesothelioma (1 paper, 2017). A usually malignant and aggressive neoplasm of the mesothelium which is often associated with exposure to asbestos. "Inhibition of ROCK2 decreased GTIIC reporter activity in H2052 and 211H suggesting that Rho/ROCK signaling also contributed to YAP activation in mesothelioma cells." (PMID 28470935, 2017).
metastatic melanoma (1 paper, 2016). A melanoma that has spread from its primary site to another anatomic site. "Furthermore, PIG3 levels decreased while ROCK1/2 levels increased in human metastatic melanomas (ROCK1 vs PIG3; r = -0.2261, P < .0001; ROCK2 vs PIG3: r = -0.1381, P = .0093)." (PMID 26464464, 2016).
myeloid malignancies (1 paper, 2023). "Interestingly, hyper-activation of ROCK2 has also been observed in myeloid malignancies, where it promotes the growth and survival of leukemic cells through the constitutive activation of the PI3K/Rho/ROCK/myosin light chain pathway." (PMID 37915324, 2023). "Interestingly, hyperactivation of ROCK2 has also been observed in myeloid malignancies, where it promotes the growth and survival of leukemic cells." (PMID 37915324, 2023).
myocarditis (1 paper, 2020). Myocarditis is a condition that is characterized by inflammation of the heart muscle (myocardium). "Using the haploinsufficient mice, we addressed whether ROCK1 or ROCK2 was implicated in the development of CD4+ T cell-mediated myocarditis." (PMID 32178482, 2020). "We found that myocarditis severity was comparable in wild-type, Rock1+/− and Rock2+/− mice at day 21 of EAM." (PMID 32178482, 2020). "Histological analysis of heart sections at day 21 of EAM showed that both Rock1+/− and Rock2+/− mice developed myocarditis with comparable severity to control wild-type mice." (PMID 32178482, 2020). "In summary, our data suggest that neither ROCK1 nor ROCK2 is critically involved in the development of CD4+ T cell-mediated myocarditis and postinflammatory fibrosis." (PMID 32178482, 2020).
overactive bladder syndrome (1 paper, 2015). "Currently, specific ROCK2 inhibitors are not available, but the present study suggests that ROCK2 might be regarded as potential therapeutic target in overactive bladder syndrome." (PMID 26468005, 2015).
paraneoplastic neurological syndromes (1 paper, 2017). "In conclusion, novel onconeural antibodies targeting ROCK2 are associated with paraneoplastic encephalitis and should be screened for when paraneoplastic neurological syndromes, especially in patients with urogenital cancers, occur." (PMID 28554330, 2017).
perihilar Cholangiocarcinoma (1 paper, 2025). "Notably, high ROCK2 expression levels were associated with poor prognoses in patients with iCCA, perihilar Cholangiocarcinoma (pCCA), and distal Cholangiocarcinoma (dCCA)." (PMID 40615369, 2025).
pneumonitis (1 paper, 2023). An inflammatory process affecting the lung parenchyma. "Furthermore, protein–protein interaction analysis showed that RELA was interrelated with CHUK, ROCK1, and ROCK2, and we chose RELA as a candidate EV protein to predict symptomatic pneumonitis." (PMID 37614219, 2023).
renal tumors (1 paper, 2017). "Formalin-fixed, paraffin-embedded sections of patient bladder and renal tumors as well as tumor-free healthy control tissue from the same surgical specimens were immunohistochemically stained with a polyclonal anti-ROCK2 antibody." (PMID 28554330, 2017).
retinal degeneration (1 paper, 2021). Degeneration of the retina. "A number of these transcripts have well-established links to retinal degeneration, including chemokine C-C motif ligand 2 (Ccl2) and rho-associated protein kinase 2 (Rock2)." (PMID 34465369, 2021).
sarcoma (1 paper, 2023). A usually aggressive malignant neoplasm of the soft tissue or bone. "In fact, it has been reported that another gene, ROCK2, often overexpressed in some types of sarcomas, may act as a DNA repair gene when MGMT is repressed, providing dacarbazine resistance to sarcomas." (PMID 37371106, 2023).
thrombosis (1 paper, 2019).
toxicity (1 paper, 2025). The degree to which an agent can damage an organism. "It is noteworthy that all target antigens (ROCK2, TOM1L1, NMD3, CPT1A, and MIT3) are expressed in normal skin according to the Human Protein Atlas, consistent with a possible relationship between autoantibodies and skin toxicity." (PMID 40828987, 2025).
Ureteral obstruction (1 paper, 2024). Obstruction of the flow of urine through the ureter. "Our mechanistic investigations exploring the ROCK2-cyclic nucleotide signaling axis are in agreement with a recent observation showing antifibrotic effects of cGMP activation in unilateral ureteral obstruction models." (PMID 38565675, 2024). "In addition, ROCK2 inhibition has been shown to be protective against tubulointerstitial fibrosis in a unilateral ureteral obstruction model." (PMID 38565675, 2024).
urothelial carcinoma of the bladder (1 paper, 2017). "Immunohistochemical staining against ROCK2 revealed an intensive expression of the antigen in infiltrating urothelial carcinoma of the bladder in our patient, making the paraneoplastic nature of ROCK2 antibodies likely." (PMID 28554330, 2017).
vascular tumor (1 paper, 2017). "shRNA-mediated knockdown of ROCK2, but not ROCK1, in xenograft vascular tumors significantly reduced tumor size and proliferative index compared to control tumors." (PMID 28709411, 2017). "Our animal studies revealed that knockdown of ROCK2, but not ROCK1, greatly reduced xenograft tumor volume in an established xenograft vascular tumor model." (PMID 28709411, 2017).
viral myocarditis (1 paper, 2024). Myocarditis that is caused by an infection with a viral agent. "ROCK2 mRNA has also been shown to be increased in viral myocarditis and suppressed by fasudil, an inhibitor of the RhoA/ROCK pathway." (PMID 38540212, 2024). "It was also shown that ROCK2 mRNA, but not ROCK1 mRNA, was significantly increased in viral myocarditis." (PMID 38540212, 2024).
tumor (98 papers, 2009 to 2025). "HK2 was found to drive glycolysis in tumor-derived pericytes and regulate the blood vessel supporting ability of pericytes by inducing Rho-associated coiled-coil containing protein kinase 2 -myosin light chain 2 (ROCK2-MLC-2) driven contractility." (PMID 36984785, 2023). "Strikingly, in GASC1-depleted cells, the expression of ubiquitination-deficient ROCK2-K121R mutant significantly enhanced tumor growth, as compared to that of WT." (PMID 33692332, 2021). "It was found that the tumor sizes of the siROCK2 group was smaller than those of NC, which indicated that lower expression of ROCK2 caused smaller OC xenografts in vivo." (PMID 30266988, 2019). "In order to validate the clinical relevance of our study wherein ROCK2 in association with RhoC regulates radiation response of tumor cells via modulation of DNA repair proteins we performed studies on clinical samples." (PMID 31488179, 2019). "It was shown that inhibition of both ROCK isoforms caused severe proliferation defects and loss of both ROCK1 and ROCK2 blocked tumor formation in mice." (PMID 28670628, 2017). "Overexpression of ROCK2 has also been linked frequently to enhanced metastatic potential (increase in migration and invasion of tumor cells) in various cancer types." (PMID 21943319, 2011). "ROCK2 was overexpressed in MM tumor tissue and implicated in the Hippo signalling pathway." (PMID 34683154, 2021). "The results of qRT-PCR and western blot analyses confirmed a significant increase in ROCK2 expression levels in CCA tissues compared to that in adjacent non-tumour tissues." (PMID 40615369, 2025). "ROCK2 plays a significant role in the occurrence and progression of multiple tumours, exhibiting high expression levels in several cancer types, including liver, gastric, colorectal, and lung cancers." (PMID 40615369, 2025). "Considering the 2 ROCK isoforms, ROCK1-mediated p-MLC activation leads to pericyte differentiation, which stabilizes vessels, whereas ROCK2 signaling in tumor pericytes seems to impair vascular function." (PMID 39286984, 2024). "In both human and mouse KRAS-driven tumours, an increase in tumour progression correlates with elevated levels of ROCK1/ROCK2 kinases." (PMID 36175301, 2023). "Among which PC-derived CCL2 can also improve tumor cell survival and tumor growth by stimulating MEK1-ERK1/2-Rho-associated coiled spiral protein kinase 2 (ROCK2)-dependent signaling in tumor cells." (PMID 37666813, 2023). "It has been found that ROCK2 protein plays an important role in the occurrence and development of tumors, mainly participating in the regulation of tumor cell survival and apoptosis as well as the invasion and metastasis of malignant tumors." (PMID 35322742, 2022). "To date, some inhibitors, including KD025 and HA-1077 targeting ROCK2, have been identified and have exhibited distinct anti-tumor effects." (PMID 35322742, 2022). "Rho‐associated protein kinases such as ROCK2 are considered to be key Rho downstream effectors, while ROCK inhibitors have anti‐tumour properties." (PMID 35277915, 2022). "Many of these mediators (e.g. MMP23D, TP73, ROCK2, USF3) have been implicated in tumorigenesis and tumor suppression or progression pathways." (PMID 33684137, 2021). "Overall, our results show that tumor-derived paracrine signal up-regulates pericyte-HK2-driven glycolysis to dysregulate its blood vessel supporting role by up-regulating ROCK2 mediated pathway." (PMID 34650057, 2021). "Our results identified GASC1 as an apical regulator of HCC progression that confers proliferative advantage to the tumor by protecting ROCK2 protein stability, which further leads to shortened survival time in HCC patients." (PMID 33692332, 2021). "It was documented that miR-139-5p plays an important role as a tumor suppressor in ovarian cancer through direct binding to ROCK-2, thus providing a novel molecular prognostic marker." (PMID 32443784, 2020).
tumor (continued). "In the AGS and SGC-7901 cell lines, circCUL2 sponged miR-142-3p to regulate ROCK2, thus modulating tumor progression." (PMID 33153478, 2020). "IHC analysis of tumor xenograft samples further indicated that the protein levels of ROCK2 were notably increased upon circCUL2 overexpression." (PMID 33153478, 2020). "Both western blot analysis and IHC assay confirmed that overexpression of ZEB1 significantly abrogated the gemcitabine-induced elevation of p-γH2AX and cleaced-PARP-1 in ROCK2-deletion tumor." (PMID 31783584, 2019). "Irrespective of the lack of exact mechanism of activation of nuclear RhoC, it is important to note that a subset of tumor cells, in the clinical samples, exhibit strong co-expression of ROCK2 and RhoC." (PMID 31488179, 2019). "The depletion of ROCK2 markedly reduced tumor growth when tumor cells were injected into immunodeficient NSG mice and completely abolished the pulmonary metastatic potential of these cells." (PMID 31878963, 2019). "IHC staining indicated a lower expression level of Lin28A and ROCK2 in the tumor tissues of A2780 Ctrl group while a higher expression level of Lin28A and ROCK2 in A2780 Lin28A group." (PMID 30266988, 2019). "The expression level of ROCK2 was positively related to the cellular nuclear antigen Ki67 which represented of the rate of tumor growth." (PMID 30266988, 2019). "We also report that both RhoC and ROCK2 are localized in the nuclear compartment in a subset of tumor cells." (PMID 31488179, 2019). "But the observation that ROCK2 inhibition and Cisplatin together radiosensitized the tumor cells better than Cisplatin alone, was the most exciting revelation." (PMID 31488179, 2019). "Collectively, ZEB1 is critical for the resistance of the SW1990/GEM cell-driven xenograft tumor to gemcitabine conferred by ROCK2." (PMID 31783584, 2019). "Clinical sample-based studies also demonstrated that ROCK2 inhibition sensitizes tumor cells to irradiation." (PMID 31488179, 2019). "The consequences of ROCK2 inhibition was also validated using clinical samples wherein we found an increased radiosensitization of tumor cells." (PMID 31488179, 2019). "The analysis of the stained sections revealed the existence of tumor cells that showed expression of either ROCK2 or DNA repair markers or both in the nuclear compartment." (PMID 31488179, 2019). "RhoC and its downstream effector ROCK2 have been independently shown to regulate tumor progression in several tumor types." (PMID 31488179, 2019). "The silencing of ROCK2 markedly reduced tumor growth and completely abolished the metastatic ability of U-2OS cells." (PMID 31878963, 2019). "Assessment of the expression of RhoC and ROCK2 in tumor-derived sections showed that both RhoC and ROCK2 were coexpressed in a subpopulation of tumor cells." (PMID 31488179, 2019). "For some antigens like ATP1A3, ITPR1, or ROCK2 an expression in tumor samples of the respective index patient was observed, pointing to a paraneoplastic autoimmune background." (PMID 30038610, 2018). "ROCK2 knockdown tumors exhibited a significantly reduced Ki67 index compared to the scrambled control, thus corroborating the effects on tumor size displayed in the ROCK2 knockdown tumors." (PMID 28709411, 2017). "Immunohistochemical staining with polyclonal rabbit anti-ROCK2 antibody (1:250) reveals strong reactivity in the patient’s invasive bladder carcinoma as well as in normal tumor free urothelium (A)." (PMID 28554330, 2017). "Even further, we detected MALAT1, miR-144-3p and ROCK1/ROCK2 expression in the formatted subcutaneous tumor nude mice specimens." (PMID 28938647, 2017). "Expression of Rho A and ROCK2 were all correlated positively tumor differentiation and TNM stage dissemination in liver and portal vein invasion." (PMID 26846339, 2016).